INS (insulin)
Diseases named in the same sentence as INS in open-access papers (continued):
Sharing a sentence is not in itself a finding about the gene and the disease.
type 2 diabetes (continued). "Despite these promising findings, further exploration into the specific molecular pathways influenced by polydatin is needed to fully understand its role in insulin production and its therapeutic potential for type 2 diabetes management." (PMID 40958722, 2025). "Obesity is featured by abnormal fat accumulation, which in turn can lead to insulin resistant phenotype and type II diabetes." (PMID 39800748, 2025). "DR also improves insulin sensitivity and mitigates systemic and skeletal muscle oxidative stress in type 2 diabetes." (PMID 40432898, 2025). "In summary, in people with CKD and type 2 diabetes, treatment with canagliflozin resulted in clinically meaningful reductions in insulin use." (PMID 40036884, 2025). "Type 2 diabetes is characterized by abnormalities in glucose metabolism, resulting from defective insulin secretion or action." (PMID 41007822, 2025). "Type 2 diabetes mellitus (T2DM) is a globally prevalent metabolic disorder characterized by impaired pancreatic β-cell insulin secretion and peripheral insulin resistance." (PMID 40648962, 2025). "Beta cell-specific PAK1 enrichment in type 2 diabetes human islets resulted in decreased beta cell apoptosis and increased insulin content." (PMID 39404845, 2025). "Applying pPSs to previously reported type 2 diabetes loci, six clusters were initially defined for impaired lipid metabolism, insulin secretion 1 and 2, adiposity, insulin action and insulin secretion/action." (PMID 40186687, 2025). "Although the publication focused on a broader range of metabolic diseases, it was observed that, specifically in patients with type 2 diabetes, IF was beneficial in the context of insulin homeostasis, among other things." (PMID 40901288, 2025). "Biochemical parameters related to type 2 diabetes including fasting glucose, serum insulin, lipid profiles, incretin hormone, liver, and pancreatic histology were evaluated." (PMID 40448078, 2025). "In type 2 diabetes, abnormalities in lipid and glucose metabolism are frequently observed due to reduced insulin sensitivity, which exacerbates metabolic dysregulation and contributes to the progression of the disease." (PMID 40958722, 2025). "Transcriptomic analysis revealed that differentially expressed genes post-celastrol treatment were associated with steroid biosynthesis, estrogen signaling pathways, type 2 diabetes, insulin secretion, meiosis, and apoptosis." (PMID 40897829, 2025). "Recent research has highlighted the pharmacological potential of bibenzyl derivatives in managing metabolic disorders, such as obesity and type 2 diabetes, primarily due to their anti-inflammatory, antioxidant, and insulin-sensitizing properties." (PMID 40218862, 2025). "IcoSema is intended for the management of type 2 diabetes that is insufficiently controlled on basal insulin or GLP-1 RAs in addition to diet, exercise and oral glucose-lowering medications." (PMID 39820580, 2025). "We previously demonstrated that youth with obesity and type 2 diabetes compared with their normoglycemic peers have higher fasting insulin concentrations, despite significantly impaired β‐cell function." (PMID 40470991, 2025). "This process results in ATP depletion and reactive oxygen species (ROS) accumulation, fueling inflammation and insulin resistance pivotal in the pathophysiology of obesity and type 2 diabetes." (PMID 40760453, 2025). "In humans, the infusion of TNF-alpha has been found to decrease muscle insulin sensitivity and glucose uptake, providing evidence of its role in the development of type 2 diabetes." (PMID 40218888, 2025). "Adiponectin is positively related to insulin sensitivity in humans and predicts development of type 2 diabetes and the metabolic syndrome." (PMID 39999040, 2025). "Impaired insulin secretion by pancreatic β-cells is a prominent feature of type II diabetes mellitus." (PMID 41011581, 2025).
type 2 diabetes (continued). "Huntington’s disease features mutant HTT (mHTT)-driven autophagy defects and oxidative stress, and epidemiology shows higher type-2 diabetes prevalence in HD; in neurons, mHTT overexpression impaired insulin signaling and triggered apoptosis." (PMID 41226780, 2025). "Omentin is a key adipokine involved in glucose metabolism and insulin sensitivity, with accumulating evidence suggesting that its reduced levels contribute to the pathophysiology of type 2 diabetes mellitus (T2DM)." (PMID 41149627, 2025). "A decreased abundance of Akkermansia muciniphila led to impaired insulin secretion and glucose homeostasis in lean individuals with type 2 diabetes." (PMID 39967592, 2025). "Peroxisome proliferator-activated receptor gamma (PPARG) ligands are potent insulin sensitizers used in type 2 diabetes treatment." (PMID 40564064, 2025). "The roles of insulin and inflammation have also been extensively studied in obesity and type 2 diabetes." (PMID 40821816, 2025). "Even more important was the observation that fasting plasma insulin concentrations continued to rise from normoglycemia to impaired glucose tolerance to type 2 diabetes." (PMID 41009753, 2025). "Probably, the group using “insulin only” also includes people with type 2 diabetes with complications like renal failure that can contraindicate the use of several non-insulin GLD." (PMID 41350985, 2025). "Presently, a multicenter RCT is being conducted to assess the effects of adding metformin to insulin therapy for pregnant women diagnosed with type 2 diabetes." (PMID 40552127, 2025). "The initial response of beta cells during the onset of type 2 diabetes is to adapt their insulin secretion to maintain euglycaemia and to compensate for peripheral insulin resistance." (PMID 40471239, 2025). "Unlike most previous studies, the present research targets both individuals with type 1 diabetes and insulin users among patients with type 2 diabetes." (PMID 40471961, 2025). "This is particularly beneficial for people with type 2 diabetes, who need to manage insulin sensitivity and glucose fluctuations." (PMID 40026940, 2025). "From the perspective of disease progression, early-stage type 2 diabetes is marked by a reduction in insulin sensitivity within peripheral tissues." (PMID 41301787, 2025). "Adiponectin is a well-known anti-inflammatory, anti-atherosclerotic, and insulin-sensitizing factor involved in the regulation of glucose and lipid metabolism, affecting insulin sensitivity, and protecting against type 2 diabetes and cardiovascular diseases." (PMID 40724644, 2025). "Type 2 diabetes (T2D) is a chronic metabolic disorder characterized by insulin resistance and impaired insulin secretion, resulting in sustained hyperglycemia." (PMID 39796271, 2025). "High concentration of glucose (glucotoxicity) induces VDAC-1 overexpression in insulin-secreting β-cells in type 2 diabetes (T2D) patients." (PMID 40649921, 2025). "Characterizing insulin secretion and insulin action in older people would be useful for developing appropriate strategies for the prevention and treatment of type 2 diabetes." (PMID 40002793, 2025). "Supporting this, a survey‐based study in the US found that over 90% of patients with type 2 diabetes and their physicians preferred a once‐weekly insulin regimen compared with daily injections." (PMID 41152194, 2025). "Insulin therapy plays a crucial role in managing both Type 1 and Type 2 diabetes, but traditional methods, especially subcutaneous injections, present challenges such as pain, discomfort, and difficulty in achieving stable blood sugar control." (PMID 40352348, 2025). "This is of particular importance in insulin-treated type 2 diabetes, where inter alia 24-h blood glucose monitoring is essential." (PMID 40901288, 2025). "In type 2 diabetes, the proportion of ST8Sia1+ β cells often increases, and these cells exhibit higher basal insulin secretion and weakened glucose responses." (PMID 41301440, 2025).
type 2 diabetes (continued). "In summary, short‐term intensive insulin therapy is an effective way to maintain sustained euglycemic remission in patients with newly diagnosed type 2 diabetes, even in those at very high baseline glucose levels." (PMID 40747755, 2025). "Short‐term intensive insulin therapy assists patients with newly diagnosed type 2 diabetes and significant hyperglycemia to achieve glycemic remission." (PMID 40747755, 2025). "Its ability to stimulate insulin secretion was found to be largely preserved in patients with type 2 diabetes (T2DM), providing a clear rationale for its development as a major therapeutic target." (PMID 41515907, 2025). "The results demonstrated that a hypocaloric oat-based diet led to a significant reduction in total insulin dosage and HbA1c levels in insulin-treated outpatients with type 2 diabetes." (PMID 40724270, 2025). "These outcomes have direct consequences for optimising health-related outcomes for people with type 2 diabetes, and have implications for the long-term cost-effectiveness of providing access to isCGM for people with type 2 diabetes on insulin therapies." (PMID 39460755, 2025). "The insulin-mediated suppression of plasma BCAAs was reduced in individuals with type 2 diabetes compared with individuals with obesity (main effect p=0.017), but with no additional effect of acute exercise." (PMID 40404819, 2025). "Oral medications and insulin are effective treatments for type 2 diabetes, but insulin therapy is eventually indicated for patients once maximal doses of oral medications are no longer sufficient to control blood glucose levels." (PMID 40242444, 2025). "Three of nine patients (33%) were current smokers, and two (22%) had insulin-treated type 2 diabetes." (PMID 41149853, 2025). "This study aimed to evaluate the impact of glucagon-like peptide-1 receptor agonist (GLP-1 RA) plus insulin therapy on long-term cardiovascular and microvascular outcomes in patients with type 2 diabetes (T2D), with the goal of optimizing treatment strategies." (PMID 41011236, 2025). "A survey about CGM implementation for patients with type 2 diabetes on insulin was distributed to all PCPs in the Department of Veterans Affairs (VA) health system from October 2023-April 2024." (PMID 40057678, 2025). "Troglitazone treatment in insulin-resistant lean or obese type 2 diabetes patients can lower PAI-1 concentrations and is associated with enhanced fibrinolytic activity linked to lower plasma insulin levels and improved glycemic control." (PMID 39966987, 2025). "A decline in mitochondrial efficiency leads to increased oxidative stress, which not only impairs insulin signaling pathways but also promotes inflammatory responses, further contributing to the progression of type 2 diabetes." (PMID 40076782, 2025). "Glucose-lowering medication was recorded for 11/12 donors with type 2 diabetes: two (18%) were insulin-treated, six (55%) on oral medication and three (27%) on diet alone." (PMID 40991018, 2025). "MiR-203a-3p, which is predicted to directly target leptin, is enriched in pathways related to leptin and insulin signaling, type 2 diabetes, and taste perception, among others in our data." (PMID 41047117, 2025). "In type 2 diabetes, the number of beta cells decreases, which results in reduced insulin production and increased insulin resistance, primarily in the liver, skeletal muscles, and adipose tissue." (PMID 40281899, 2025). "GLP-1RAs were originally developed for managing type 2 diabetes by enhancing insulin secretion and reducing appetite." (PMID 40722294, 2025). "In contrast, type 2 diabetes is a metabolic disorder characterized by the reduced sensitivity to insulin, leading to elevated blood glucose levels." (PMID 41009460, 2025). "In metabolic disorders like type 2 diabetes and obesity, ER stress in key metabolic organs such as the liver and pancreas impairs insulin signaling, leading to insulin resistance and beta-cell dysfunction." (PMID 41009381, 2025).
type 2 diabetes (continued). "In this systematic review and meta‐analysis of six RCTs including 3967 adults with type 2 diabetes, we compared once‐weekly efsitora alfa with standard once‐daily insulin." (PMID 41152194, 2025). "Glucagon-like peptide-1 receptor agonists, used for the treatment of type 2 diabetes, have been reported to exert two beneficial effects on pancreatic islet hormone secretion: the promotion of insulin secretion and the suppression of glucagon secretion." (PMID 40429740, 2025). "In obesity and type 2 diabetes, both arms fail—the insulin signal that moves the GLUT4 transporter to the cell surface is blunted, and the liver continues to manufacture glucose even when circulating levels are already high." (PMID 40710568, 2025). "Future studies should investigate the effects of Cirsiliol in insulin-resistant or obese models to better understand its potential in treating DCM in patients with type 2 diabetes or metabolic syndrome." (PMID 41381837, 2025). "Sodium–glucose cotransporter (SGLT) 2 inhibitors were originally developed to lower glucose levels for the treatment of individuals with type 2 diabetes (T2D) in an insulin-independent manner by inhibiting glucose reabsorption from the proximal renal tubules." (PMID 40564007, 2025). "In metabolic disorders, such as obesity and type 2 diabetes, inflammatory cytokines interfere with insulin signaling and lipid metabolism, perpetuating insulin resistance and glycemic dysregulation." (PMID 41465826, 2025). "This cross-sectional study aimed to evaluate the knowledge and practices of insulin use among patients with type 1 and type 2 diabetes and to identify factors influencing these practices." (PMID 40471961, 2025). "Magnesium is an essential cofactor for numerous enzymes that participate in carbohydrate metabolism, and it also plays a role in insulin action, glucose regulation, and the development of type 2 diabetes." (PMID 40094652, 2025). "Another class of insulin sensitizers are thiazolidinediones (TZDs: pioglitazone and rosiglitazone), which are primarily generally used to treat type 2 diabetes by improving insulin sensitivity." (PMID 40430499, 2025). "According to current evidence, several case reports have documented the successful use of omalizumab in managing insulin hypersensitivity in patients with both type 1 and type 2 diabetes." (PMID 40869188, 2025). "Type 2 diabetes is characterized by the body’s inability to regulate glucose levels properly, either due to insufficient insulin production by the pancreas or because cells develop insulin resistance." (PMID 40399988, 2025). "We developed a microsimulation model to estimate the impact of treating patients with type 2 diabetes who use insulin with GLP-1 receptor agonists or SGLT-2 inhibitors in LMICs." (PMID 40245017, 2025). "The study group consisted of insulin-naive adults with type 2 diabetes, baseline HbA1c of 7.0–10.5% (53–91 mmol/mol), BMI of at least 25 kg/m2, and stable weight." (PMID 41465455, 2025). "Since this receptor increases insulin sensitivity, it is frequently the target of type 2 diabetes medicines." (PMID 40066031, 2025). "Inhibition of DPP‐4 activity specifically results in higher glucagon‐like peptide‐1 levels, and increases the half‐life of circulating insulin, thereby enhancing glycemic control in individuals with type 2 diabetes." (PMID 40905017, 2025). "The ability of insulin to reduce plasma BCAAs was significantly attenuated in participants with type 2 diabetes compared with both lean individuals (studies I and IV) and individuals with obesity (studies I, II and IV) (all p<0.05)." (PMID 40404819, 2025). "It has been suggested that the anabolic response to protein is mainly preserved in type 2 diabetes (T2D) when insulin and amino acid availability are adequate." (PMID 41305580, 2025). "Our goal was to identify which determinants to prioritize for improvement efforts focused on supporting CGM use for patients with type 2 diabetes on insulin." (PMID 40057678, 2025).
type 2 diabetes (continued). "In type 2 diabetes, the Kumamoto study found that intensive insulin therapy for seven years improved nerve function." (PMID 41280964, 2025). "Insulin lispro is a rapid-acting analog of human insulin, commonly used to treat type 1 and type 2 diabetes via subcutaneous administration." (PMID 40733109, 2025). "Over time, these β-cells become exhausted, and their insulin production cannot keep up with the insulin demand of resistant cells, resulting in elevated blood sugar levels and type-2 diabetes." (PMID 41514592, 2025). "The emergence of once-weekly basal insulin analogues represents a transformative shift in the treatment landscape of type 1 and type 2 diabetes, addressing long-standing barriers to insulin treatment." (PMID 40937414, 2025). "Plasma insulin levels were higher in men with type 2 diabetes compared with control participants, driven primarily by one participant with an outlier insulin value of 498 pmol/l." (PMID 40580209, 2025). "Such mutations compromise mitochondrial function due to disturbances in insulin secretion, making people more likely to develop type 2 diabetes and MIDD." (PMID 39835172, 2025). "RGZ is a potent insulin sensitizer and is thus used to lower blood glucose in humans with type 2 diabetes." (PMID 39951006, 2025). "Patients with type 2 diabetes and cardiovascular disease should be started on either a GLP-1RA, SGLT-i, or both in high-risk cases, while simultaneously tapering any prescribed insulin regimen." (PMID 40637950, 2025). "Often, healthcare providers need to convince patients with Type 2 diabetes to initiate insulin, supporting the belief that insulin cannot be stopped." (PMID 41236132, 2025). "Our study demonstrated that the serum cortisol concentration was related to insulin secretion in patients with untreated type 2 diabetes." (PMID 40296149, 2025). "Women with insulin-insufficient GDM appear to have pregnancy outcomes that are comparable to those of the normoglycaemic population, but women with altered insulin secretion still appear to have substantial risks of type 2 diabetes postpartum." (PMID 39621104, 2025). "Type 2 diabetes develops when insulin production declines alongside increased hepatic gluconeogenesis due to liver insulin resistance." (PMID 41155203, 2025). "In humans with type 2 diabetes, 3 months of anakinra treatment increased insulin secretion and decreased the ratio of proinsulin to insulin, indicating improved beta cell function." (PMID 39496966, 2025). "Glycemic control was poor in many type 2 diabetes patients, with factors like insulin use, fasting glucose levels, physical inactivity, and hypertension contributing significantly." (PMID 40385776, 2025). "This systematic review and meta-analysis was to evaluate and compare the efficacy and safety profiles of IDegLira versus insulin degludec in the management of type 2 diabetes (T2D)." (PMID 40958912, 2025). "Type II diabetes mellitus (T2D) is a pathological state characterized by insulin resistance, hyperglycemia, and subsequently impaired glucose-mediated insulin secretion." (PMID 40427579, 2025). "Dietary intervention is an adjunct therapy for type 2 diabetes, where matching insulin doses to carbohydrate, fat, and protein intake during meals remains critical." (PMID 40509444, 2025). "Type 2 diabetes mellitus (T2DM) increases the risk of developing AD, and conversely, AD patients often present with glucose intolerance and elevated plasma insulin levels." (PMID 41444683, 2025). "We conducted a systematic review and meta‐analysis of randomised controlled trials (RCTs) comparing once‐weekly BIF with once‐daily insulin degludec in type 1 and type 2 diabetes." (PMID 40509887, 2025). "Possible mechanisms include disturbances of insulin signaling pathways, alterations in glucose and lipid metabolism, as well as induction of inflammation in promoting type 2 diabetes development." (PMID 41144600, 2025).